CD44 (CD44 molecule (IN blood group))
Diseases named in the same sentence as CD44 in open-access papers (continued):
Sharing a sentence is not in itself a finding about the gene and the disease.
tumor (continued). "The cell adhesion molecule CD44, especially its V3 and V6 variants, is abundantly expressed on tumor cells and confers an invasive phenotype." (PMID 31294922, 2019). "CD44 has multiple splice variants, including the ubiquitous V4, which along with V3 and V6 is closely related to tumor metastasis." (PMID 31294922, 2019). "Data from preclinical models showed that larger tumor burden was associated with more aggressive tumor growth associated and increased CD44 expression." (PMID 31315262, 2019). "The CD44v8-10 to standard CD44-ratio (total ratio of all CD44 alternative splicing isoforms) in urothelial cancer has been shown to be closely associated with tumor progression and aggressiveness." (PMID 30072631, 2018). "One example is the CD44v8-10-to-standard CD44-ratio (total ratio of all CD44 alternative splicing isoforms) in urothelial cancer that has been shown to be closely associated with tumor progression and aggressiveness." (PMID 30072631, 2018). "For example, CD44 knockout mice show reduced epidermal differentiation and CD44 down-regulation in tumour cells is associated with stem cell loss whereas over-expression of CD44 drives tumour progression and promotes CSC properties." (PMID 29568372, 2018). "Metastasis of tumor is stimulated by secretion of hyaluronan by fibroblasts in stroma associated with tumor as well as by overexpression of CD44, a major cell hyaluronan receptor—both of which are induced by lactates." (PMID 30235348, 2018). "SC niches and the tumor matrix are rich in HA and CD44 and the HA-CD44 association facilitates SC and CIC arrest." (PMID 30211160, 2018). "In relation to clinical features, CD44 expression was associated with tumor infiltrations (p = 0.065)." (PMID 30430079, 2018). "The effect of GCB, TQ and their combination against tumor associated stem cell clone (CD44+/CD24−) was assessed using flow cytometry." (PMID 30076320, 2018). "CD44 can act as co-receptors and/or stabilize receptor tyrosine kinase receptors causing tumor cell proliferation and invasion." (PMID 29747682, 2018). "High expression of CD44, the main HA receptor, is associated with a normal and tumor stem cell-like phenotype." (PMID 30564299, 2018). "In MCF10DCIS tumors, human nuclei+/CD44high cancer cells detected by a human-specific CD44 antibody at the tumor-stroma interface were mostly E-cadherin- and associated with periostin at laminin-5+ basement membrane, which became prominent after PTX treatment." (PMID 29507310, 2018). "The expression of the stem-cell-associated markers—CD133 and CD44—in these cells was highly variable from one tumor sample to another and in the same sample at different times." (PMID 29652830, 2018). "For example, a study reported that the antibody CD44, one of the most established and common surface markers of CSCs, can suppress tumor progression and cause apoptosis of leukemic cells." (PMID 28290053, 2018). "In 2000, Vis and coworkers reviewed their findings from 1997 and republished the Spearman correlation coefficient −0.49 (p = 0.001) as evidence of an association between CD44 and tumor stage." (PMID 29682524, 2018). "CD44 is a lymphocyte hyaluronan receptor that has been implicated as a marker in cancer stem cells, and contributes to their metastasis in the tumor microenvironment." (PMID 30557297, 2018). "To clarify the role of the GSCs that highly expressed CD44 in the tumor progression, we investigated the possible association between the degree of expression of CD44 in the tumor periphery and imaging features on MRI and survival in GBM patients." (PMID 30210550, 2018).
tumor (continued). "Attempts to isolate CD44hi CGC by flow or simply observing the cells after tumor dissociation in cell culture led to rapid loss of CD44 expression and failure of the cells to expand in culture." (PMID 29930325, 2018). "CD44v6 is currently the most established tumor antigen among the CD44 splice variants, with a large expression difference between healthy and malignant tissue, which is a key advantage for molecular imaging." (PMID 29097914, 2017). "In one study of OCSCC, irregular staining of CD44 in tumor cells is shown to be associated with poor tumor differentiation and advanced stage." (PMID 28626726, 2017). "CD44 has been found associated to the sphere-forming, self-renewing and tumor-initiating fraction of OC cells in different experimental models." (PMID 28320418, 2017). "Among CD44 variants, CD44 variant 6 (CD44v6) has been implicated in carcinogenesis, tumor progression, and recurrence in a variety of human cancers, identified recently as the marker of CSCs in brain tumors, colorectal and bladder carcinomas." (PMID 28507278, 2017). "As a multifunctional cell surface receptor, CD44 has been associated in the development of many neoplasms because of its modulating ability in cancer progression such as conveying cell adhesion and cell migration that aids the expansion of tumors." (PMID 28403901, 2017). "PrPC interacts with the cell surface protein CD44, a marker for several types of cancer stem-like cells that associates with tumor-initiating and metastatic capacities and promotes epithelial-mesenchymal transition (EMT) and tumor growth after resection." (PMID 28412969, 2017). "Given that CD44+/CD24- cells in TNBC have been shown to possess tumor-initiating properties and to be associated with resistance to chemotherapy, we analyzed the two surface markers in both docetaxel sensitive and resistant TNBC cell lines." (PMID 29190901, 2017). "CD74 and CD44 were observed to accumulate in cytoplasmic compartments, suggesting they associate with each other to facilitate tumour growth and metastasis." (PMID 29190904, 2017). "CD44v6 (CD44 variant exon 6) is the major CD44 isoform that regulates tumor invasion, progression and metastasis." (PMID 28403901, 2017). "The CD44 variant v6 in particular promotes tumor progression and metastatic potential in some cancers." (PMID 29077041, 2017). "CD44, a multifunctional surface receptor has been implicated in tumor progression in different cancers including MPM." (PMID 28403901, 2017). "There is evidence suggesting that MMP-9 and CD44 associate in mouse and human tumor cells resulting in MMP9 activity localization on the cell surface." (PMID 28326306, 2017). "While the functional and clinical implications of CD44 variants have been investigated in various tumor types, only limited information is available on their role in CSC." (PMID 28320418, 2017). "CD44 is associated with major cell functions like adhesion, motility, proliferation, stemness and is, as such, an actor of the tumor phenotype." (PMID 28418857, 2017). "Tumor cells are associated with tumor stem cells, but CD44+CD117+ stem T cells regulate T-cell proliferation." (PMID 28279199, 2017). "Several studies have associated certain CD44 splice variants with tumor cell invasion, metastasis, and disease progression, in particular isoforms containing CD44 exon variant 6 (CD44v6)." (PMID 29097914, 2017). "CD44, a glycoprotein of cell-surface, is closely associated with tumor metastasis and cancer stem cell (CSC) differentiation, which, regardless of its variation, has been demonstrated to play an important role in the progression of malignancies including GC." (PMID 28415792, 2017). "In this study, we identified EMP3 as a potential tumor-associated gene that is highly expressed in CD44-high primary GBM." (PMID 27527869, 2017). "CD44 has been implicated in leukocyte homing and activation, wound healing, cell migration, and tumor metastasis." (PMID 27107424, 2016).
tumor (continued). "As CD44 overexpression is linked to tumor aggressiveness and metastatic potential in many tumors, it is an attractive therapeutic target." (PMID 27507056, 2016). "Our finding showed that BRCA1 knockdown induced the expansion of the CD49f+EpCAM+ subpopulation in the CD44+CD24– cell subset of MCF10DCIS tumor cells, confirming the relationship between BRCA1 deficiency and luminal progenitors." (PMID 27556296, 2016). "CD44 positivity is associated with higher cell mobility, invasiveness, and shorter tumor-free survival, and it promotes the maintenance of stemness in GC cells." (PMID 27729869, 2016). "Accumulating evidence indicates that major HA-CD44 signaling pathways involve a specific variant of CD44 isoforms; however, the particular variant almost certainly depends on the type of tumor cell and the stage of the cancer progression." (PMID 27200096, 2016). "Tumor-infiltrating CD8+ T cells were CD44+, mostly with loss of homing receptors CD62L and CCR7 expression, and composed of two main sub-populations CD45RA− and CD45RA+, suggesting a relatively differentiated status." (PMID 27306834, 2016). "Loss of either CD44 or E-cadherin leads to impairment of epidermal cell adhesion, thereby promoting invasion of malignant tumor cells into the neighboring tissues." (PMID 27271600, 2016). "Reduction of ESRP1 in tumor cells was evaluated by immunohistochemistry, associated with microsatellite stability and switch to mesenchymal splice signatures of FGFRs, CD44, ENAH and CTNND1(p120-catenin)." (PMID 27650542, 2016). "Consistently, inhibition of FZD6 also markedly reduced MES-associated CD44 expression in MES brain xenograft tumours." (PMID 27698350, 2016). "CD44 expression and alternative splicing were also implicated in tumor metastasis and epithelial-to-mesenchymal transition of cancer stem cells." (PMID 27505250, 2016). "The conjugate selectively accumulated in CD44-positive tumors and caused dramatic tumor shrinkage and efficient elimination of CD44-positive cell populations following irradiation." (PMID 27302409, 2016). "The present results indicate that CD44 expression is positively associated with higher tumor TNM stage, as well as poor OS for patients with HCC." (PMID 27330410, 2016). "the Kokko study reported a significant association between tumor CD44 overexpression and heavy smoking of more than 10- pack years (P=0.009)." (PMID 28008391, 2016). "Expression of CD44 has been closely linked to tumor progression, metastasis, and treatment resistance processes in various cancers." (PMID 27330410, 2016). "The immunohistochemical characterization of the HemSC-derived tumorspheres showed expression of GLUT1, the diagnostic marker of IH, as well as high levels of CD44, a well-established tumor stem cell marker." (PMID 27786256, 2016). "This study suggests that TNF-α derived from tumor-associated macrophages is linked to CD44 upregulation via NF-κB signaling in ccRCC." (PMID 27293448, 2016). "A trend of CD44 expression associated with different histological grading and aggressive behavior of this tumor." (PMID 26821610, 2016). "CD44+/CD24low is a marker for tumor-initiating cells and its expression is associated with EMT like Claudin-low tumors." (PMID 27941987, 2016). "As a cellular adhesion molecule and a major extracellular glycoprotein, the hyaluronic acid receptor CD44 has been implicated in tumor invasion and metastasis in breast, lung, and gastrointestinal cancers." (PMID 27253518, 2016). "In summary, this meta-analysis indicated that CD44 expression was associated with tumor TNM stage in HCC." (PMID 27330410, 2016). "Expression of CD44 and particularly the variant CD44v isoforms is upregulated in carcinomas and, as an adhesion molecule, plays a role in tumor cell invasion and metastases." (PMID 26930718, 2016).
tumor (continued). "Due to paucity of studies regarding involvement of CD44 variants in tumor angiogenesis and cancer stem cells, we discuss its functions in tumor cells in general and how cell-specific perturbation of HA-CD44v interaction can be used to inhibit cancer growth." (PMID 26448753, 2015). "CD24−/CD44+ tumor cells or ALDH1-positive tumor cells were significantly associated with poor survival in a recent meta-analysis, although ALDH1 expression alone does not significantly predict outcomes." (PMID 26405647, 2015). "Loss of CD44 attenuated tumor cell adhesion to endothelial cells and reduced cell invasion but did not affect proliferation in vitro." (PMID 25888636, 2015). "CD44 is one of the cell surface markers associated with cancer stem cells in several types of tumor, including breast, prostate, pancreas, ovarian, and colorectal cancers." (PMID 26464794, 2015). "Because of the close association of high HA levels with malignancy in many tumor types considerable experimental evidence implicates HA and its main receptor CD44 variants in tumor progression both in cell and animal models." (PMID 25999946, 2015). "Tumor growth and metastasis is associated with increased levels of soluble CD44 (sol-CD44), which is detected in plasma from cancer patients, indicating increased proteolytic activity and matrix remodeling by CD44." (PMID 25999946, 2015). "CD44 is a transmembrane receptor associated with aggressive tumor growth, proliferation, and metastasis." (PMID 25605020, 2015). "Taken together, these results suggest that cholesterol-lowering causes disordered CD44 localization, raft-dependent CD44 shedding, and the suppression of tumor cell migration that is dependent on hyaluronan’s size." (PMID 26347743, 2015). "Other works indicated that variants of CD44 are significantly amplified in numerous tumor types compared with normal processes." (PMID 25909172, 2015). "Different CD44 variant (CD44v) isoforms appear to confer the malignant properties of increased tumor cell growth and cancer progression." (PMID 26029210, 2015). "In summary, CD44 standard and variant isoforms are closely associated with many signaling pathway proteins that drive tumor development and progression in many types of cancer." (PMID 25954275, 2015). "The predominant CD44 isoform expressed in the nervous system is the standard form, although the presence of CD44 splice variants has been demonstrated in normal human brain tissue, as well as in certain primary tumours of the brain and peripheral nerve." (PMID 25999819, 2015). "In these clinical samples CD44 expression was associated with tumor cells directly lining the vasculogenic structures." (PMID 26189059, 2015). "Some previous studies have found that the lymphocyte-homing receptor CD44, a cell-surface biomarker, is strongly associated with tumor progression and metastasis, and is commonly used as biomarker of CSCs." (PMID 25993512, 2015). "CD44 is recognized as a marker of cancer stem cells, which are a small population of stem-like cells residing in tumor tissues that can cause tumor formation, recurrence, and metastasis." (PMID 24387290, 2014). "The germline polymorphisms in colon CSC genes have demonstrated that CD44 is involved in predicting tumor recurrence in patients with colorectal cancer." (PMID 24699672, 2014). "CD44 has been reported to be involved with tumor growth and metastasis and has also been implicated as a CSC marker in head and neck squamous cell cancer (HNSCC)." (PMID 24410905, 2014). "CD44, a transmembrane receptor for hyaluronan is associated with aggressive tumour growth, metastasis and resistance to therapy." (PMID 24884875, 2014). "CD44 variant isoforms are highly expressed in carcinomas of epithelial origin and relate to tumor progression and metastatic potential of some cancers." (PMID 24133067, 2014).
tumor (continued). "The v6 splice variant of CD44 is involved in tumorigenesis, tumor cell invasion, and metastasis and is expressed preferentially in squamous cell carcinomas." (PMID 24991539, 2014). "Our findings also support pre-existing evidence indicating a direct molecular interaction of Cdc42 and CD44 in association with tumor cell-actin cytoskeleton, by demonstrating that they synergize in altering vessel architecture in brain slices." (PMID 25032689, 2014). "CD44v4–v7 are thought to be carcinoma-associated variants of CD44, which is a surface molecule that promotes tumor metastasis." (PMID 24727741, 2014). "Noteworthy, selective deletion of a tumor-specific variant of the CD44 molecule from the complex, CD44v9, leads to loss of the xCT transporter from the surface of the tumor cells with consequent suppression of tumor growth." (PMID 25228443, 2014). "Intratumoral and systemic injection of miR-34a into mice grafted with human PCa tumors resulted in reduced tumor volumes and lung metastasis and was associated with prolonged survival by suppressing the adhesion molecule CD44." (PMID 25250334, 2014). "The active protease reduced CD44 molecules at tumor cell surface interfering with cell adhesion, causing a cytostatic effect in vitro." (PMID 24788523, 2014). "The grouping into two groups by the analyzed variants of CD44 (hCD44, hCD44s, hCD44v6, and hCD44v8) showed a significant difference in tumor related survival only for CD44s and CD44v6 (P <0.05 and P <0.02, respectively)." (PMID 24491153, 2014). "CD44 is an important member of the adhesion molecule family and is closely associated with tumor invasion and metastasis." (PMID 24944709, 2014). "The SMAD1/CD44 interaction also is associated with reversible dormancy of CSCs along with the potential for tumor recurrence and metastasis in prostate cancer." (PMID 25471937, 2014). "The dramatic increase in CD44 VE expression level seen in the metastatic tumours means, that the variants most likely play a role in metastasis formation." (PMID 23342032, 2013). "CD44 is a molecule with multiple variants, and future characterization of these variants is necessary for production of ideal mAbs for specific tumor types." (PMID 23314952, 2013). "CD44v6, a variant isoformof CD44, regulates tumor invasion and metastasis formation, has been shown as a protein marker for metastatic behavior in breast, colorectal and gastric cancers." (PMID 24019861, 2013). "One-third PH was associated with an almost threefold increase in relative tumor mass (MRI volumetry: 2.8-fold and transcript levels of CD44: 2.3-fold)." (PMID 23385555, 2013). "EGFR is of specific interest as the tumor-specific constitutively active variant III is associated with CD44+/CD24− subpopulation of breast CSCs33." (PMID 23982413, 2013). "CD44, the principal receptor for the extracellular matrix component hyaluronan (HA), is frequently found overexpressed in tumor cells and has been implicated in metastatic spread in various cancer types." (PMID 23565227, 2013). "CD44v6 as a kind of CD44 variant isoforms, is regarded to be responsible for tumor lymphangiogenesis and lymph node metastasis." (PMID 24019861, 2013). "Upon phosphorylation at S102, P-YB-1S102 translocates to the nucleus and promotes the induction of growth factors such as EGFR, Her-2, and the MET receptor as well as the tumor-initiating-cell (TIC)-associated genes CD44 and CD49f." (PMID 23593654, 2013). "Aberrant CD44 expression is therefore inextricably linked to genetic alterations that lead to tumor growth and metastasis." (PMID 23445749, 2013).